TNF (tumor necrosis factor)
Diseases named in the same sentence as TNF in open-access papers (continued):
Sharing a sentence is not in itself a finding about the gene and the disease.
atherosclerosis (continued). "Although SWCNT exposure was associated with atherosclerosis acceleration, we did not observe significant differences in the plasma levels of IL-6, IL-10, MCP-1, TNF-α, or IFN-γ." (PMID 17431486, 2007). "One of the aims of the present study was to compare vascular TNF-α and TNF receptor expression in a mouse strain that spontaneously develops atherosclerosis (apoE-/-/LDL receptor-/- mice) with control mice that does not develop atherosclerosis unless challenged with a high-fat diet (C57BL/6)." (PMID 23675033, 2007). "TNF-α blockade has shown harmful effects in heart failure, suggesting elevated TNF-α may be compensatory, whereas IL-1β inhibition reduced cardiovascular events post-myocardial infarction, indicating a deleterious role in atherosclerosis." (PMID 41552677, 2025). "The literature suggested FCGR3A(CD16A) + monocytes were significantly increased in apoE-/- mice with high fat diet, which might correlate with aortic MMP-9 mRNA expression and serum TNF-α level, indicaitng FCGR3A involved in the progression of atherosclerosis through inflammatory pathways." (PMID 41348730, 2025). "As a result, TNF‐α‘s involvement in promoting the transcytosis of LDL across endothelial cells contributes to the retention of lipoproteins in the vascular walls, which could further exacerbate the development of atherosclerosis." (PMID 40161001, 2025). "The last but not the least, studies show that pro-inflammatory molecules such as interleukin-1, interleukin-6, and tumor necrosis factor-α both stimulate osteoclast activity, which could raise β-CTX levels, and promote atherosclerosis by triggering endothelial dysfunction and plaque inflammation." (PMID 41050279, 2025). "Finally, in vivo (rat/zebrafish) and in vitro (cell models) validations remain essential, exemplified by the Moluodan concentrated pill downregulating TNF-α/PI3K/p-Akt in gastritis and the Buyang huanwu decoction modulating the AKT1/MAPK1/PIK3CA axis against atherosclerosis." (PMID 40732361, 2025). "While we lacked data on advanced inflammatory markers like TNF-α or IL-6, which may mediate the malnutrition-inflammation-atherosclerosis (MIA) pathway, these warrant future study." (PMID 40984946, 2025). "Interleukin-3 (IL-3), tumor necrosis factor-α (TNF-α), and interferon-γ have been identified as key factors that activate macrophages, endothelial cells, and vascular smooth muscle cells, thereby exacerbating local inflammation and promoting the progression of atherosclerosis." (PMID 41383228, 2025). "Additionally, TNF-α interacts with SGLT2 (sodium-glucose cotransporter 2), promoting vascular inflammation and endothelial dysfunction via the NADPH oxidase-angiotensin II pathway, thereby accelerating atherosclerosis." (PMID 40661082, 2025). "The mechanism of action of kaempferol in treating OP may involve up-regulating the expression of AKT1 and down-regulating the expression of MMP9, while participating in the Atherosclerosis-related signaling pathways, AGE/RAGE signaling pathway, and TNF signaling pathway." (PMID 38528143, 2024). "CNDs as low as 0.03 mg/mL significantly inhibited TNF-α-mediated expression of IL-8 and adhesion molecule ICAM-1, two key molecules that are responsible for the activation and the firm adhesion of monocytes to activated endothelial cells for the initiation of atherosclerosis." (PMID 38397822, 2024). "Combined with present and previous studies, we uncovered the involvement of HOTAIR in atherosclerosis, at least in part, we demonstrate that HOTAIR alleviates the formation of foam cell and inflammatory reaction by inhibiting miR-19a-3p in atherosclerosis through TNF-α/miR-19a/HBP1/MIF pathway." (PMID 38250607, 2024).
atherosclerosis (continued). "CD8+ T cells promote atherosclerosis through two mechanisms, first by leading to vascular inflammation by the secretion of proinflammatory cytokines such as interferon‐gamma (IFN‐γ) and tumor necrosis factor-alpha (TNF-α) and second by increasing apoptotic cell numbers in lesions." (PMID 39463572, 2024). "Interestingly, recent data suggest that T-bet–expressing invariant natural killer T (iNKT) cells and type I innate lymphoid cells (ILCs) aggravate atherosclerosis through the elaboration of pro-inflammatory cytokines IFN-γ and TNF-α, while Tregs control the activation of NKT cells and ILCs." (PMID 39378110, 2024). "Patients with type 2 diabetes (T2DM) and macrovascular atherosclerosis showed higher levels of circulating IL-6 compared to patients with atherosclerosis and no diabetes, and in combination with levels of TNFα, were better at predicting atherosclerosis development in T2DM patients." (PMID 38256155, 2024). "Isoliquiritigenin, a licorice extract, attenuated TNF-α-induced NLRP3 inflammasome activation and pyroptosis in human umbilical vein endothelial cells by targeting sirtuin-6, which could be beneficial in the management of atherosclerosis." (PMID 37765019, 2023). "Therefore, we propose the following mechanism to explain the atherosclerosis inhibitory effect of moxonidine: moxonidine inhibits the expression of inflammatory genes (e.g., IL-1, MCP-1 and TNF-α), which subsequently may inhibit the oxidation of LDL." (PMID 36835270, 2023). "Thus, the present data showed earlier atherosclerosis effects, such as the expression of adhesion molecules, but no late signals of unresolved inflammation, such as local TNF-α, in the thoracic segments of the aortas." (PMID 37892238, 2023). "In our human plaque tissue slice experiments, we observed decreased the secretion of TNFα, IL-8 and IL-10 after STAT5 inhibition, suggestive of a pro-inflammatory activity of STAT5 in plaque and identifying macrophage STAT5 as a candidate for intervention in human atherosclerosis as well." (PMID 37920458, 2023). "Moreover, in the immune and inflammatory pathways promoting atherosclerosis, activated T cells are involved which are a source of RANKL and pro-inflammatory cytokines (such as tumor necrosis factor α (TNF-α), interleukin-1 (IL-1), and interleukin - 6 (IL-6)), that up-regulate RANKL expression." (PMID 36060948, 2022). "Furthermore, through the modulation of inflammatory responses, with reduce expression of TNF-α, IL-6, IL-1, and IL-8 of monocytes, f TNF-α, IL-6, IL-1, and IL-8 of monocytes, Vitamina D may influence the pathophysiology of atherosclerosis." (PMID 35276762, 2022). "Additionally, Morin could reduce the TNF-α and IL-6 levels by inhibiting the PI3K/AKT/NF-κB pathway atherosclerosis which considered a chronic inflammatory disease." (PMID 35705830, 2022). "Therefore, USF1 may be involved in atherosclerosis by regulating the expression of IL-1β, VEGF, TNF-α, and IL-6." (PMID 35783856, 2022). "Atherosclerosis and thrombosis may be exacerbated by senescent ECs that produce increased levels of IL-1, IL-6, IL-8, IL-15, monocyte chemoattractant protein-1 (MCP-1), TNF, and other mediators." (PMID 36082127, 2022). "ECD is initiated by multiple inflammatory factors in atherosclerosis; when the endothelium is injured, inflammatory mediators, including vascular cell adhesion molecule-1 (VCAM-1), intercellular adhesion molecule-1 (ICAM-1), interleukin 6 (IL-6), and tumor necrosis factor α (TNF-α)are expressed." (PMID 34899318, 2021).
atherosclerosis (continued). "Moreover, targeted therapies, such as tumor necrosis factor α (TNF-α) inhibitors may dampen secondary inflammatory atherosclerosis and may prevent major CV events (MACE), particularly in anti-TNF-responders." (PMID 34680168, 2021). "CyPA is known to promote atherosclerosis through stimulation of low-density lipoprotein uptake, decrease of endothelial nitric oxide synthase (eNOS) expression, increase of vascular cell adhesion molecule 1 (VCAM-1), and induction of tumor necrosis factor alpha (TNFα)." (PMID 34552938, 2021). "Additionally, 51 KEGG pathways were significantly enriched (P-adjusted < 0.05), including the AGE-RAGE signaling pathway in diabetic complications, lipid metabolism and atherosclerosis, NF-kappa B signaling pathway, IL-17 signaling pathway, PPAR signaling pathway, and TNF signaling pathway." (PMID 34899707, 2021). "Humanin treatment also inhibits the high glucose-induced secretion of TNF-α and IL-1β and reduces the expression of VCAM-1 and E-selectin, thus preventing hyperglycaemia-induced attachment of the monocytes to the vascular cells, endothelial dysfunction and atherosclerosis progression." (PMID 34445477, 2021). "For example, interleukin (IL)-6 and tumor necrosis factor (TNF)-α, members of the inflammatory cytokine family released from vascular smooth muscle cells, endothelial cells, monocytes, macrophages, and so forth, have been shown to be deeply involved in atherosclerosis." (PMID 34366780, 2021). "For example, IL18R1 was enriched in the TNF signaling pathway and cytokine–cytokine receptor interaction; PFKFB3 was enriched in fructose and mannose metabolism and HIF-1 signaling pathway; IL1R2 was enriched in hematopoietic cell lineage and fluid shear stress and atherosclerosis." (PMID 34336943, 2021). "Inflammatory cytokines including interleukin-1beta (IL-1β), tumor necrosis factor alpha (TNF-α), transforming growth factor-beta (TGF-β), and interferon-gamma (IFN-γ) induce endothelial dysfunction and the acquisition of mesenchymal properties, therefore contributing to atherosclerosis." (PMID 34604359, 2021). "Thus, these potential target proteins were closely related to TNF, HIF-1, FoxO, and PI3K-Akt signal pathways, suggesting that these factors and pathways may mediate the beneficial effects of GBH on atherosclerosis." (PMID 33321972, 2020). "Thus, the combination of previous and current research results revealed that TNF, CXCL8, SOCS3 and TNFAIP3 may be involved in chronic inflammatory lesions that eventually result in atherosclerosis, CAD or IS." (PMID 32164735, 2020). "In this report, we define a novel model of CD8 T cell involvement in atherosclerosis whereby CX3CL1 and IL-15 operate in tandem within the vascular endothelium to promote infiltration by activated CX3CR1+ memory CD8 T cells that drive further endothelial activation via TNF." (PMID 32976527, 2020). "In addition, they demonstrated that CB-ECFCs were able to decrease the expression of mediators of inflammation and atherosclerosis produced by allogeneic lymphocytes and monocytes (IL-1β, IL-8, PGF, ALOX-5, TNFα, CSF-2, MMP-1, MMP-9) more significantly than adult ECFCs." (PMID 32381102, 2020). "The adaptive immune response is related to tumor necrosis factor (TNF) produced by T cells or type I interferon (IFN), and some inflammatory factors, such as IL-12, IL-23, and IL-18, can produce proplaque factors and accelerate the progression of atherosclerosis." (PMID 32733941, 2020). "Although the precise roles of IL-2 in atherosclerosis are not well clarified, substantial research evidences have demonstrated the potent roles of IL-2 in stimulating lymphocytes to produce inflammatory cytokines, such as IL-6, TNF-α, and IFN-γ." (PMID 31379468, 2019).
atherosclerosis (continued). "Background and Aim: Previously, we found that short chain fatty acids (SCFA) inhibit LPS or TNFα-induced endothelial inflammatory responses and excessive vascular cell adhesion molecule-1 (VCAM-1) expression, two important steps in the development of atherosclerosis." (PMID 29875665, 2018). "Since endothelial cell-specific inhibition of NF-κB protects mice from atherosclerosis, and since ANRIL is a downstream target of TNFα/NF-κB signaling, targeting TNFα or NF-κB may theoretically be considered to be athero-protective via inhibiting ANRIL-YY1-mediated IL-6/8 production." (PMID 29868613, 2018). "Overproduction of inflammatory mediators such as NF-κB, TNF-α, COX-II, and NO produced by macrophages, neutrophils, and other immune cells is very much involved in the pathogenesis of chronic diseases, for example, atherosclerosis, arthritis, type 2 diabetes, and cancer." (PMID 28900464, 2017). "Since adalimumab is an exclusive human specific TNF-α inhibitor we could not test its effect on atherosclerotic plaque development in an experimental mouse model of atherosclerosis." (PMID 27467817, 2016). "In addition, tumor necrosis factor-α (TNF-α), a pro-inflammatory cytokine released in response to pathological conditions, is elevated in atherosclerosis and may promote its pathogenesis." (PMID 26095681, 2015). "Hence, we speculated that cilostazol inhibits the signaling of NF-kB and decreases transcription of different proteins, including ICAM-1, VCAM-1, E-selectin, TNF-α, interleukin-6 (IL-6), AGE, and ligands for RAGE in human atherosclerosis." (PMID 25666934, 2015). "Considering that atherosclerosis is an inflammatory disease, then we investigated the effects of proinflammatory factors on TrkB expression in HAECs by administration with or without TNF-α, ox-LDL." (PMID 26431274, 2015). "The included studies used different blood-derived markers of atherosclerosis, such as: high sensitivity CRP (hsCRP), vasogenic endothelial growth factor (VEGF), interleukins (IL) IL-6 and IL-18, osteopontin (OPN), osteoprotegerin (OPG) and tumor necrosis factor-alpha (TNF-α)." (PMID 25984600, 2015). "Nevertheless, MCP-1 inhibition resulted in decreased TNFα, IL-6, tissue factor and PAI-1 in an inflammation model induced by stress in mice, suggesting a beneficial effect not only in inflammation but also in the prothrombotic state in the presence of atherosclerosis." (PMID 26578976, 2015). "Initially, it has been hypothesized that C. pneumoniae may contribute to atherosclerosis through inflammation, as evidenced by an increased production of inflammatory cytokines (IL1-β, IL-6, IL-8 and TNF-α) and chemokines found in vascular cells involved in the atherosclerotic process." (PMID 25561227, 2014). "An insight into the pathogenesis of atherosclerosis revealed that uptake of highly oxidized LDL particles by scavenger receptors in macrophages leads to foam cell formation, and expression of scavenger receptors is regulated by cytokines, such as TNF-α and interferon-γ (IFN-γ)." (PMID 24733347, 2014). "Because TNF-α-induced expression of multiple pro-inflammatory genes is significantly blocked by (R)-DOI in whole aortic arch, 5-HT2A receptor activation may be an effective approach to develop novel therapeutics for atherosclerosis." (PMID 24098382, 2013). "Levels of serum IL-1β and TNF-a dropped, mRNA and protein expression of E-sel, VCAM-1, ICAM-1 and MCP-1 in the aorta of rabbits were respectively down-regulated by the treatment of kaempferol, indicating that kaempferol can prevent atherosclerosis by alleviating vascular inflammation." (PMID 23895132, 2013). "EAT secretes various proinflammatory adipokines like interleukin (IL)-1, IL-6, IL-8, IL-10, tumor necrose factor (TNF) α, leptin, macrophage chemoattractand protein 1 (MCP-1), type I plasminogen activator inhibitor (PAI-1), resistin that provide a metabolic milieu that promotes atherosclerosis." (PMID 23133630, 2012).
atherosclerosis (continued). "Also, unlike our previous observations on patients with severe disease undergoing treatment with the chimeric anti-TNF-alpha monoclonal antibody-infliximab, no progression of subclinical atherosclerosis was observed after 1 year of adalimumab therapy." (PMID 22899879, 2012). "Atherosclerosis and NAFLD progression are both accompanied by inflammation development which involves several factors, including various chemokines (monocyte chemoattractant protein 1; MCP-1), cytokines (tumor necrosis factor-α; TNF-α), interleukin-6 (IL-6) and C-reactive protein (CRP)." (PMID 23226761, 2012). "The prevailing hypothesis that atherosclerosis is a Th1 disease is supported by studies in which mice lacking IFN-γ or the IFN-γ receptor, TNF-α, or the Th1 transcription factor T-bet have reduced atherosclerosis." (PMID 22844641, 2012). "Specifically, EBI3 and p35 are strongly expressed in advanced atherosclerotic plaque in humans and can be up-regulated by TNF-α and IFN-γ stimulation in cultured human primary aortic smooth muscle cells, suggesting IL-35 may be involved in atherosclerosis progression." (PMID 23285065, 2012). "The same group also showed that omentin inhibits TNF-α induced COX-2 expression by inhibiting the JNK signaling pathway in human umbilical vein endothelial cells, suggesting that omentin might prevent atherosclerosis by modulating the vascular endothelial inflammatory state." (PMID 22108456, 2011). "In summary, this study shows that medial TNF-α and TNF receptor expression precedes lesion formation in the atherosclerosis-susceptible apoE-/-/LDL receptor-/- mouse, whereas the aortas of control C57BL/6 mice were essentially negative for TNF-α and TNF receptor immunoreactivity." (PMID 23675033, 2007). "Mechanistic studies have verified that AK136714 directly targets HuR (ELAVL1) to promote the mRNA stability of TNF-α and IL-1β and increases the transcription of Bim, indicating that AK136714 could function in atherosclerosis and provide potential novel drug targets for atherosclerosis intervention." (PMID 37418054, 2024). "Additionally, IL-17 inhibitors have shown superior efficacy over TNF-α inhibitors and IL-12/23 inhibitors in reducing non-calcified plaque burden, suggesting that IL-17 inhibitors may offer added benefits in managing atherosclerosis in this patient population." (PMID 39739136, 2024). "The KEGG pathway enrichment analysis suggested that the treatment mechanism of IO for ORG might be related to TNF signaling pathway, HIF-1 signaling pathway and the pathways of glycolipid metabolism, such as AGE-RAGE signaling pathway in diabetic complications and lipid and atherosclerosis." (PMID 39234117, 2024). "Thus, we investigated the effect of GV1001 on the TNF-α-induced EndMT using HUVEC cells and found that GV1001 notably inhibited the EndMT process induced by TNF-α, a major proinflammatory cytokine responsible for the development and progression of atherosclerosis." (PMID 37628753, 2023). "Our in vitro data also show that F. nucleatum promotes the secretion of inflammatory factors, such as TNF-α, IL-1β, IL-6, and the chemokine MCP-1 during foam cell formation, which suggests that the increased systemic inflammation level induced by F. nucleatum might accelerate atherosclerosis." (PMID 35359716, 2022). "Previous studies suggested that TNF-α, and other inflammatory cytokines such as IL-17A, may has a role in inducing the formation of neutrophil extracellular traps (NETs), which is a specific type of cell death involved in many diseases including both VET and atherosclerosis." (PMID 33519488, 2020). "IL-1 and TNF-α could induce oxidation of LDL and promote aggregation of oxidized LDL, and then the oxidized LDL can induce local vascular cells to produce MCP-1, which can promote monocyte recruitment and increase the inflammatory response and enhance the progression of atherosclerosis." (PMID 25598757, 2014).